HBD (hemoglobin subunit delta)
Diseases named in the same sentence as HBD in open-access papers (continued):
Sharing a sentence is not in itself a finding about the gene and the disease.
head and neck cancer (1 paper, 2023). A primary or metastatic malignant neoplasm affecting the head and neck. "In the present narrative review, the aim will be to discuss the changes in the hBD expression profile during the onset and progression of head and neck cancers." (PMID 36980171, 2023).
Hyperglycemia (1 paper, 2024). An increased concentration of glucose in the blood. "Current evidence does not support the fact that hyperglycemia, long-term vitamin use, pregnancy, or aging regulate the periodontal status via their effects on oral hBD expressions." (PMID 39204254, 2024).
laryngeal papillomas (1 paper, 2006). "Although our study was performed on laryngeal papillomas, hBD expression is likely upregulated in other papillomavirus-induced lesions including both cutaneous and mucosal genital warts since these lesions share very similar pathology." (PMID 16961924, 2006).
myopia (1 paper, 2023). "We report a rare case of a 20-year-old female patient with type 1 DM, hemoglobin D (HbD) heterozygote variant and high myopia of -10.00 spheric diopters, and describe the retinal microvascular alterations visible on OCT angiography (angio-OCT)." (PMID 37761301, 2023).
pneumonia (1 paper, 2013). An acute, acute and chronic, or chronic inflammation focally or diffusely affecting the lung parenchyma, caused by an infection in one or both of the lungs (by bacteria, viruses, fungi, or mycoplasma.). "Active TB cases were separated from all other groups (i.e. LTBI, HC and non-TB pneumonia) based on expression of PIGC (p = 0.045), GLDC (p = 0.044) and HBD (p = 0.025)." (PMID 23375113, 2013).
Respiratory tract infection (1 paper, 2005). An infection of the upper or lower respiratory tract. "Finally, although the members of the hBD peptide family have similar amino acid structures, hBD-4 is suggested to play a different role than the other hBDs in the defense against respiratory tract infections." (PMID 16269090, 2005).
Stroke (1 paper, 2025). Sudden impairment of blood flow to a part of the brain due to occlusion or rupture of an artery to the brain. "Therefore, monitoring changes in HbO, HbT, and HbD using fNIRS can provide a deeper understanding of the pathophysiological mechanisms of post-stroke motor dysfunction and offer important biomarkers for motor recovery." (PMID 41426298, 2025).
vasculitis (1 paper, 2021). "have shown that the expression of HBD has been considerably increased in patients with vasculitis." (PMID 34504491, 2021).
vitiligo (1 paper, 2023). Generalized well circumscribed patches of leukoderma that are generally distributed over symmetric body locations and is due to autoimmune destruction of melanocytes. "The serum level of HBD-1 had a non-significant association with DEFB-1 genotypes in vitiligo patients (p = 0.611) or in the control group (p = 0.716)." (PMID 36535830, 2023).
tumor (14 papers, 2010 to 2025). "This novel mechanism is the first evidence of an hBD molecule orchestrating an in vivo outcome and demonstrates its importance in establishing a tumor-associated inflammatory microenvironment, which supports growth and progression of tumors." (PMID 20544025, 2010). "For example, expression comparison of the hemoglobin subunit delta encoding gene HBD in the TCGA_LUAD_2016 cohort shows that tumor samples have decreased HBD expression compared to normal samples, whereas samples from smokers and non-smokers have similar expression levels." (PMID 30532070, 2019). "Considering the human beta defensin expression median value of the BPH tissue samples baseline, we examined the hBD expression of the tumor tissue samples depending upon pre-existing antibiotic treatment." (PMID 38674148, 2024). "Many defensins, such as PvD1, HBD-1 and HBD-3 have been shown to perturb tumour cell migration, often via the disruption of cytoskeleton dynamics." (PMID 35204765, 2022). "Moreover, these strains have also been shown to enhance the expression of antimicrobial peptides like human β-defensin (hBD) and anti-inflammatory cytokines such as IL-10, suggesting a dual role in both direct tumor suppression and immune modulation." (PMID 41305617, 2025). "Thus, altered hBD expression and tumor promoting effects are argued to be cancer-origin specific." (PMID 32111012, 2020). "However, treatment of head and neck SCC (HNSCC) cell lines with hBD3 improved resistance against cis-platin, indicating that higher hBD expression may enhance tumor survival." (PMID 22808251, 2012). "WB analysis of serum and tumor tissue specimens confirmed the upregulation of eight proteins: APOA1, HBB, CAH1, HBD, LPA, SAA4, PF4V1, and APOE." (PMID 39194522, 2024). "Interestingly, the high abundance identifies were consistent both in the tumor and normal tissues in EESCC and EDAC at the protein level, including HBB, HBA1, HBD, ACTB, ALB, etc.." (PMID 35397555, 2022). "Ketimine reductase mu‐crystallin and hemoglobin subunit delta encoded by CRYM and HBD, respectively, did not seem to be associated with tumor progression." (PMID 33955587, 2021). "Because both cancer cohorts have no HGB-related clinical data available, we quantified a tumor’s HGB level as the average expression levels of four HGB-related genes (HBA1, HBA2, HBB and HBD)." (PMID 39415833, 2024).
infection (9 papers, 2010 to 2025). The state of being infected such as from the introduction of a foreign agent such as serum, vaccine, antigenic substance or organism. "Additional wound healing parameters were evaluated at day 10 post-injury/infection to seek for other effects of the hBD-2 hydrogels." (PMID 40663184, 2025). "Heme/hemoglobin metabolism was enriched in groups 1, 2, and 4, with four common genes (ALAS2, AHSP, HBD, and CA1) that are associated with the immune response to infection." (PMID 41839673, 2025). "The hBD adjuvant promotes innate and adaptive host defense by recruiting immature dendritic cells, naive memory T cells, and monocytes toward the region of infection." (PMID 38075876, 2023). "We analyzed the production of beta-defensins (hBD) and cathelicidin LL-37 during the infection of primary limbo-corneal fibroblasts with M. tuberculosis (MTB), M. abscessus (MAB), and M. smegmatis (MSM)." (PMID 25436879, 2013). "Thus, it has been shown that, in keratinocytes IL-22 induces the production of antimicrobial peptides such as human beta defensin-2 (HBD-2) which plays a key role in host defense against infection." (PMID 38431633, 2024). "Unsurprisingly, HbA1, HbA2 and HbD gene expression was less in ALV-J infected birds, although until now, little has come to light on the molecular relationship between hemoglobin synthesis and ALV infection." (PMID 21637603, 2010). "Besides, the results expose that both free hBD-2 and hBD-2 hydrogels exhibited a substantial reduction in MRSA load within the wound bed compared to blank hydrogels, particularly evident by day 10 post-injury/infection." (PMID 40663184, 2025). "In the healthy colon, hBD-2 and hBD-3 are absent and only induced during inflammation or infection." (PMID 21151692, 2010).
cancer (6 papers, 2006 to 2024). A tumor composed of atypical neoplastic, often pleomorphic cells that invade other tissues. "While these results may, on-the-surface, appear to be inconsistent, if studies are segregated based on cell lines used, type of cancer being investigated, and the specific hBD studied, a clearer picture unfolds." (PMID 31131258, 2019). "The functional significance of altered hBD expression in cancer is unclear at present." (PMID 22808251, 2012). "IFI27, CRYM, HBD, and IFITM3 in TEPs were positively related to the pan‐cancer stage and essential for diagnosing cancers with a sensitivity of 59.1%, 57.8%, 54.3%, and 60.9%, and a specificity of 90.9%, 89.1%, 72.7%, and 94.5%, respectively." (PMID 33955587, 2021). "Seven TEPs mRNAs were discovered in our study: RSL24D1, IFI27, CRYM, HBD, IFITM3, FCGR2A, and KLHDC8B in TEPs, which are mainly enriched in protein binding, extracellular matrix, and metabolic process, and may be used for cancer diagnosis." (PMID 33955587, 2021). "In this study, 7 TEPs mRNAs were verified, including RSL24D1, IFI27, CRYM, HBD, IFITM3, FCGR2A, and KLHDC8B, which may be used for cancer detection." (PMID 33955587, 2021). "Consequently, we believe alternative TEPs mRNAs, including RSL24D1, IFI27, CRYM, HBD, IFITM3, FCGR2A, and KLHDC8B mRNA, can potentially serve as non‐invasive biomarkers for diagnosing cancers and can even predict the prognosis of pan‐cancer." (PMID 33955587, 2021). "First of all, in analyzing the TCGA and Pancancer_2020 cohorts, we have used the mean expression levels of HBA1, HBA2, HBB and HBD to represent HGB levels of cancer patients, which may not fully reflect blood HGB levels." (PMID 39415833, 2024). "Therefore, studies addressing hBD dysregulation in various cancers are not generalizable and comparisons should be avoided." (PMID 31131258, 2019).
adenocarcinoma (1 paper, 2016). A common cancer characterized by the presence of malignant glandular cells. "Consistent with our proteomic data, mRNA expression of APEX1, HYOU1, PDIA4, NANS, LRPPRC, EPRS and COPG1 were significantly (Mann–Whitney U < 0.05) higher in adenocarcinoma compared to control whereas mRNA abundance of HBG1, HBG2, HBD, and PTRF were significantly (Mann–Whitney U < 0.05) lower." (PMID 27799870, 2016).
bacterial infections (1 paper, 2021). "It has been shown that certain virulence factors released by pathogens are involved in the downregulation of hBD production; however, most of the existing evidence derives from studies on bacterial infections." (PMID 35049960, 2021).
hematologic disease (1 paper, 2022). "As a first target for this method, we chose two sites: a 6-bp region spanning three codons within the human hemoglobin subunit beta (HBB) gene that is of great importance for adaptation and hematologic disease, and the identical, paralogous region within the hemoglobin subunit delta (HBD) gene." (PMID 35031571, 2022).
inflammation (1 paper, 2024). Aberrant reaction of the microcirculation characterized by movement of fluid and leukocytes from the blood into extravascular tissues. "Our study found that in the univariate analysis between groups, the indicators related to myocardial inflammation and myocardial damage showed statistical differences, such as hs-CRP, CK-MB, LDH, LD1, α-HBD, AST, and ALT." (PMID 38228722, 2024).
HBD also shares sentences with these, for which no sentence is quoted: Hypertension (2 papers); malignant melanoma (2); Arrhythmia (1); atopic dermatitis (1); bacterial vaginosis (1); chronic periodontitis (1); colorectal cancer (1); dementia (1); dental caries (1); heart failure (1); inflammatory bone diseases (1); iron deficiency (1); ischemic stroke (1); metastatic cancer (1); metastatic tumor (1); microcytic anemia (1); neonatal anemia (1); Neurological Disease (1); oral squamous cell carcinoma (1); osteosarcoma (1); Parkinson’s (1); red blood cell disorders (1); type 2 diabetes (1).